HMOX1 (heme oxygenase 1)
Diseases named in the same sentence as HMOX1 in open-access papers (continued):
Sharing a sentence is not in itself a finding about the gene and the disease.
Sepsis (continued). "This study elucidates that lipopolysaccharide‐binding protein (LBP) ameliorates sepsis‐induced myocardial injury by activating the nuclear factor erythroid 2‐related factor 2/heme oxygenase‐1 (NRF2/HO‐1) signaling pathway, thereby suppressing lipid peroxidation and ferroptosis." (PMID 40969909, 2025). "In addition, researchers have also found that nuclear factor-red lineage 2p45-related factor 2 (Nrf2)-mediated heme oxygenase-1 (HO-1) signaling pathway plays a key role in the protective effect against sepsis-induced acute lung injury." (PMID 39417448, 2024). "Notably, proteins like serine protease inhibitor (Serine protease inhibitor) and heme oxygenase-1 (Hmox1), previously explored in sepsis, were among the identified targets." (PMID 38188141, 2024). "In addition, the study found that silencing of miR-31 protected against intestinal barrier dysfunction by inhibiting the NF-κB/HIF-1α pathway and targeting HMOX1 during sepsis." (PMID 38187112, 2023). "In addition, the time-course expressions of Ptgs2, Hmox1, and Slc7a11 in the model of sepsis-induced cardiac injury induced by the injection of LPS were also analyzed." (PMID 37424906, 2023). "Heme oxygenase-1 can also induce autophagy in the liver following CLP-induced sepsis." (PMID 36978809, 2023). "Furthermore, the Kaplan–Meier analysis demonstrated that patients with higher HMOX1 expression have a higher probability of developing sepsis and septic shock compared to those with a lower expression." (PMID 37367740, 2023). "Also, our study showed that the high expression of Hmox1 had a close relationship with sepsis-induced cardiac injury." (PMID 37424906, 2023). "Our findings suggest that HMOX1 mRNA expression on ICU admission could be useful as a prognostic marker for sepsis and septic shock development." (PMID 37367740, 2023). "In general, the conclusions drawn from these reports are consistent with the results in our research, that is, Hmox1, Epas1, Sirt1, Slc3a2, Jun, Plin2 and Zfp36 collectively promote the development of sepsis-induced liver failure by interacting with B cells and NK cells." (PMID 35923893, 2022). "Therefore, we screened the ferroptosis-related genes (Hmox1, Epas1, Sirt1, Slc3a2, Jun, Plin2 and Zfp36) in this study through bioinformatics analysis, and found that these genes were highly expressed in sepsis-induced liver failure model." (PMID 35923893, 2022). "In addition, some researches show that Hmox1 protects against heme injury, and can regulate Hmox1 protein expression in response to oxidative damage, including the oxidative damage in sepsis." (PMID 35923893, 2022). "The identification of ferroptosis-related genes Hmox1, Slc3a2, Jun and Zfp36 in the present study contribute to our understanding of the molecular mechanism of sepsis-induced liver failure, and provide candidate targets for the diagnosis and treatment of the disease." (PMID 35923893, 2022). "Hmox1 was confirmed in this study playing an important role in sepsis." (PMID 35923893, 2022). "In addition, labile heme can be catalyzed by the enzyme heme oxygenase-1 (HO-1), whose expression and activity increase in the late phase of sepsis." (PMID 36209190, 2022). "As a result, Hmox1, Slc3a2, Jun and Zfp36 may become new therapeutic targets for sepsis-induced liver failure in the future." (PMID 35923893, 2022). "In addition, we constructed a mouse model, and confirmed through H & E staining, TUNEL staining and qRT-PCR that Hmox1, Slc3a2, Jun and Zfp36 were significantly related to sepsis-induced liver failure." (PMID 35923893, 2022). "There are some studies have shown that activation of the PI3K/Akt pathway can promote the expression of heme oxygenase-1 (HO-1), which in turn plays an anti-apoptotic or anti-inflammatory role in the oxidative damage response and improves multiple organ dysfunction in sepsis." (PMID 36406124, 2022). "HMOX1 is the enzyme responsible for heme scavenging in sepsis." (PMID 32899231, 2020).
Sepsis (continued). "Importantly, during sepsis the cytoprotective enzyme HMOX1 is upregulated and thus helps in combating sepsis-induced tissue injury." (PMID 32899231, 2020). "Furthermore, the current study showed that the rats with sepsis exhibited higher expressions of miR-31, HMOX1, NF-κB, and HIF-1α in addition to decreased expressions of IκB, ZO-1, and Occludin." (PMID 30340459, 2018). "The current study aimed to investigate whether miR-31 has effects on intestinal barrier dysfunction by targeting HMOX1 through the NF-κB/HIF-1α pathway in sepsis." (PMID 30340459, 2018). "In comparison to the sepsis group, the expression of HMOX1 mRNA and protein in the ileal tissues in the miR-31 mimic and siRNA-HMOX1 groups were significantly lower (all p < 0.05), whereas significantly higher levels were observed in the miR-31 inhibitor group." (PMID 30340459, 2018). "However, the naringin’s protective effects on sepsis-induced lung injury were eliminated by zinc protoporphyrin, a heme oxygenase 1 competitive inhibitor." (PMID 27716835, 2016). "However, the administration of CORM-2 was able to increase phagocytosis, decrease circulating bacterial counts, and rescue HMOX1–/– mice from the exaggerated mortality of CLP-induced sepsis, even when applied 6 hours after the initiation of infection." (PMID 23171578, 2012). "An inhibitor of mmu-miR-7212-5p enhances Hmox1 expression and mitigates ferroptosis by diminishing Acsl4 expression, suggesting that mmu-miR-7212-5p inhibitors may represent a promising clinical therapeutic target for sepsis-related AKI." (PMID 39839617, 2024). "Moreover, our previous research revealed that Golgi stress is implicated in sepsis-induced ALI and may be modulated by heme oxygenase-1 (HO-1)." (PMID 37550659, 2023). "Similar results were obtained in the lung from a seawater instillation-induced acute lung injury rabbit or from cecal ligation and puncture-induced sepsis mice, which proved that H2 could regulate the expression of heme oxygenase-1 (HO-1), the Nrf2 downstream antioxidant protein." (PMID 38136182, 2023). "Hence, the measurement of HMOX1 gene expression on ICU admission may provide physicians with a useful tool for determining the likelihood of sepsis and septic shock occurrence, allowing for more targeted treatment." (PMID 37367740, 2023). "In addition, there have been reports indicating the involvement of Hmox1 in the regulation of iron-mediated cell death in sepsis.Therefore, LPS-treated mice and primary rat cardiomyocytes were used to confirm the expression and function of targets related to iron poisoning." (PMID 37424906, 2023). "Heme oxygenase-1 activation may attenuate sepsis-induced ERS and acute lung injury." (PMID 35759162, 2022). "Additionally, HMOX1 plays an important role in protection from polymicrobial sepsis." (PMID 32899231, 2020). "In macrophages, the most differentially expressed genes after sepsis include S100a9, S100a8, Hbb-bs, Fth1, AW112010, Spic, Cxcl2, Cd14, Hmox1, and Vcam1." (PMID 38343542, 2024). "The ferroptosis-related genes (NOX4, HMOX1, POR, SAT1, etc.)were highly expressed in sepsis-induced cardiomyopathy model." (PMID 37035738, 2023). "HMOX1, MAPK14, and TLR4 were significantly overexpressed in sepsis, compared with the control group (all P < 0.001)." (PMID 35844488, 2022). "The present study analyzed different ferroptosis-related DEGs in sepsis and healthy controls and explored the clinical value of three hub genes (HMOX1, MAPK14, TLR4) in the early diagnosis of sepsis." (PMID 35844488, 2022). "With respect to potential mechanisms for HO-1-mediated protection in sepsis, several studies have demonstrated that circulating levels of HMGB1 contribute to LPS-induced mortality in Hmox1−/− mice." (PMID 22518295, 2012). "HO-1 (HMOX1) has been shown to protect from a variety of pathologies, including sepsis, hypertension, atherosclerosis, acute lung injury, kidney injury, and pain." (PMID 21464939, 2011).
Sepsis (continued). "Notably, heme oxygenase-1 (HO-1), known for its anti-inflammatory properties, has been shown to inhibit the PI3K/Akt signaling pathway during sepsis-induced lung injury in murine models." (PMID 41041277, 2025). "In addition, the increased HMOX1 expression in the lung epithelial and endothelial cells was reversed by DIPY treatment in both LPS-induced ALI and CLP-induced sepsis mice." (PMID 39629132, 2024). "The fact that bilirubin is the result of heme degradation by HMOX-1 provides a link between our clinical observations and our ex vivo experiments, suggesting that RNH1 level play a crucial role in iron homeostasis during sepsis." (PMID 38951571, 2024). "However, the observed mRNA upregulation of ferroptosis-related factors, including Ptgs2, Hmox1 and other genes at this early time point, could represent an initial cellular response to oxidative stress, inflammation, or disrupted iron homeostasis triggered by sepsis." (PMID 39726718, 2024). "In support of our notion, previous studies demonstrated that ISO failed to elicit its beneficial effects on the treatment of sepsis when HMOX1 expression was suppressed by ZnPPIX, an HMOX1 inhibitor." (PMID 38509740, 2024). "HMOX1 mRNA expression was increased in patients who developed sepsis/septic shock compared to the non-septic group (p < 0.0001)." (PMID 37367740, 2023). "The boxplot revealed 26 differentially expressed genes between the sepsis-induced ALI and control samples: Ncf2, Slc2a6, Cd44, Txnip, Slc2a1, Ubc, Hspb1, Zfp36, Arntl, Ddit4, Tnfaip3, Txnrd1, Mt1, Hmox1, Gch1, Gclc, Stat3, Egfr, Hif1a, Bach1, Socs1, Dusp1, Cdkn1a, Fth1, Steap3, and Alox12." (PMID 37081490, 2023). "Studies have shown that in sepsis patients, HMOX1 expression was higher in non-survivors than in survivors." (PMID 35844488, 2022). "MAPK14 concentrations were significantly higher in children with sepsis than in controls (median 96.418 vs. 20.177 ng/ml, P < 0.001), whereas HMOX1 (P = 0.367) and TLR4 (P = 0.506) were not significantly different." (PMID 35844488, 2022). "Heme oxygenase-1 (HMOX1, HO-1) is a target gene of nuclear factor erythroid 2-related factor 2 (Nrf2), which has been shown to protect against a variety of pathologies including sepsis, hypertension, and atherosclerosis." (PMID 34961267, 2021). "From all above, it can be hypothesized that the miR-31, HMOX1, and the HIF-1α/NF-κB pathway exert certain effects on sepsis." (PMID 30340459, 2018). "The expression pattern of heme oxygenase-1 (HO-1) resembled the expression pattern of CSE: basal levels of HO-1 expression were high in the YGP, were reduced with CAD, and were further attenuated with the combination of CAD and sepsis (p = 0.001)." (PMID 28321823, 2017). "Low-grade sepsis in response to colon puncture and ligation is toxic in Hmox1−/− mice but not WT mice (Hmox1+/+) and i.v. heme promotes tissues damage and leads to a severe “high grade” sepsis." (PMID 26175690, 2015). "Lack of HMOX1 in mice resulted in an exaggerated lethality after cecal ligation and puncture (CLP), which caused polymicrobial sepsis." (PMID 23171578, 2012). "Administration of free heme to wild-type (Hmox1+/+) mice subjected to low-grade microbial infection (nonlethal) was sufficient to elicit a lethal form of severe sepsis." (PMID 22518295, 2012). "Specifically, MaR1 upregulated the expression of Nrf2 and heme oxygenase-1 (HO-1) in a dose-dependent manner and inhibited phosphorylation of p38, ERK1/2, NF-κB p65 and IκBα, promoting an anti-inflammatory M2 macrophage phenotype in sepsis-induced acute liver injury mice." (PMID 39372413, 2024). "The aim of this study was to investigate the gene expression profile of HIF1A, ISG15, HK2, LDHA, HMOX1, EPO, and VEGFA under the setting of sepsis and septic shock, and furthermore to evaluate whether any of these molecules has potential value as a prognostic factor." (PMID 37367740, 2023).
Sepsis (continued). "In these studies, the serum or plasma levels of heme oxygenase (HO-1) protein were measured, with little to no data regarding HMOX1 mRNA expression in sepsis patients." (PMID 37367740, 2023).
breast carcinoma (206 papers, 2008 to 2026). "In human breast cancers, tumor expression of the heme catabolizing enzyme heme oxygenase-1 (HO-1/HMOX1) is positively associated with macrophage abundance." (PMID 42106562, 2026). "We present evidence that TMEs with an active type I IFN response exist in human breast cancer, and that expression of the gene for HO-1 (HMOX1) within these tumors is associated with prognosis." (PMID 40627458, 2025). "It is worth noting that HMOX1 mRNA, which encodes HO-1, was significantly higher in tumor tissues than in their corresponding normal tissues in 5 out of 17 common cancer types, including breast cancer." (PMID 37217939, 2023). "In fact, evidence shows that fasting‐mimicking diets can downregulate heme oxygenase 1 (HO1) expression in breast cancer cells, making them more susceptible to CD8+ cytotoxic T cells, possibly by countering the immunosuppressive effect of regulatory T (Treg) cells." (PMID 34646521, 2021). "Taken together, these findings indicate that the expression of PTGS2, NFE2L2, and HMOX1 correlates with poor clinical outcomes and may be exploited as diagnostic and/or therapeutic targets in breast cancer." (PMID 33801351, 2021). "A complex of DSF and copper increases lipid peroxidation in breast cancer cells, leading to a dramatic increase in HMOX1 activity, which in turn causes cells to undergo iron death, but the researchers have not further explored whether this compound causes cells to undergo copper death." (PMID 38585632, 2024). "Mammary tumors harboring Hmox1 knockdown had a significant decrease in tumor growth rate and number of pro-metastatic CD206+ macrophages upon treatment with αPD-1." (PMID 42106562, 2026). "In mouse mammary tumors, knockdown of Hmox1 significantly decreased tumor growth and lung metastasis." (PMID 42106562, 2026). "To assess the clinical relevance in breast cancer, we examined the association between type I IFN signaling, CD8+ T cell infiltration (via CD8A), and HO-1 (HMOX1) expression." (PMID 40627458, 2025). "A specific inhibitor of heat-shock protein 32 (HSP32) and heme oxygenase-1 (HO-1), zinc protoporphyrin IX (ZnPPIX), has also shown potential effects against breast cancer growth through HO-1 inhibition in vitro and in vivo." (PMID 39003350, 2024). "Many studies have reported that high expression of HMOX1 induces ferroptosis in colon cancer cells, breast cancer cells, and others." (PMID 38245706, 2024). "HMOX1 has been demonstrated to promote tumour progression and metastasis in multiple cancers, such as glioma, colorectal cancer, melanoma, and breast cancer." (PMID 39457550, 2024). "Compounds like BAY 11-7085 can induce ferroptosis through the Nrf2-SLC7A11-HO-1 pathway, and overexpression of heme oxygenase-1 (HO-1), encoded by HMOX1, has been observed in MDA-MB-231 breast cancer and DBTRG-05MG glioblastoma cells." (PMID 38322268, 2024). "In mouse, HMOX1 activity increased tumor growth and angiogenic potential, as well as decreased apoptosis in lung cancer progression, whilst in rat and human breast cancer cells, HMOX1 activity inhibits proliferation." (PMID 38982523, 2024). "Heme oxygenase-1, which increases the cellular free iron pool, can further enhance ferroptosis in breast cancer cells." (PMID 39867656, 2024). "Curcumin significantly restricts the survival of breast cancer cells via upregulating many ferroptosis target genes involved in redox regulation, in especial heme oxygenase-1 (HO-1)." (PMID 37191432, 2023). "The upregulation of Nrf2 target, heme oxygenase 1, reduces the M1 polarization in breast cancer TAMs, while inhibition of HO-1 diminishes that effect." (PMID 35268568, 2022). "CXCR3-B mediates growth inhibition or apoptosis via p38/MAPK activation following the downregulation of heme oxygenase 1 (HO1) and the translocation of Bach1 and Nrf2 in human renal cancer cells and breast cancer cells." (PMID 36483597, 2022).
breast carcinoma (continued). "The upregulated expression of heme oxygenase -1 (HO-1) in breast cancers has an inhibitory effect on cancer cell proliferation and invasion, and displays a dual role in ferroptotic cells, which depends on intracellular oxidative stress levels." (PMID 36505465, 2022). "Several published pieces of evidence support the overexpression of HMOX-1 in several human malignant tumors, including kidney, gastrointestinal, lung, and breast cancers." (PMID 35957802, 2022). "Reduction in stress oxygenase enzyme Heme Oxygenase-1 by FMD increased immunogenicity via cytotoxic CD8+ T cells infiltration in mammary tumors and overall improved response to chemotherapy." (PMID 35186923, 2022). "HMOX1 has been previously shown to be involved in drug resistance of breast cancer cells by preventing apoptosis and autophagy, since siRNA knockdown of HMOX1 enhanced the cytotoxicity of doxorubicin in MDA-MB-231 and BT549 cells." (PMID 34681275, 2021). "In fact, leptin has been found to upregulate antioxidant enzymes such as superoxide dismutase (SOD), catalase (CAT), and heme-oxygenase 1 (HO-1), but decreased lipid peroxidase in colorectal and breast cancer cells." (PMID 33535537, 2021). "- In breast cancer cells, the activity of Heme Oxygenase-1 (HO1) increases the intracellular iron levels, thus inducing migration and invasion of breast cancer cells." (PMID 34988012, 2021). "Subsequently, using antibody array analysis, TChal was found to increase heme oxygenase-1 (HO-1) expression in TChal-treated breast cancer cells." (PMID 34631505, 2021). "One such isolate, compound 121 inhibited breast cancer cell growth via down-regulation of the NF-κB and up-regulation of the Heme oxygenase-1 (HO-1) pathways in a dose-responsive manner, with an IC50 value of 1.6 μM." (PMID 34885716, 2021). "In clinical studies, HO-1 protein or mRNA (HMOX1) correlated positively with breast cancer progression." (PMID 34832904, 2021). "HMOX1 suppress breast cancer invasion through inhibiting the expression of matrixmetalloproteinase-9 (MMP9)." (PMID 34109210, 2021). "HMOX1 also predicted poor overall survival and decreased relapse free survival for breast cancer patients, demonstrating a role for HO-1 in tumor progression." (PMID 34832904, 2021). "15d-PGJ2 inhibits NF-κB and AP-1-mediated MMP-9 expression and invasion of MCF-7 breast cancer cells employing a heme oxygenase-1 (HO-1)-dependent mechanism." (PMID 34335286, 2021). "The probabilities of relapse free survival (RFS) among ER-PR-HER2- breast cancer patients who received chemotherapy were significantly reduced with an increased Hmox-1 transcript level." (PMID 33809707, 2021). "Hmox1 mRNA expression levels of tumor-infiltrating myeloid cells were enhanced in the PTX-treated 4T1 breast cancer group relative to an untreated 4T1 breast cancer group." (PMID 33809707, 2021). "The results demonstrated that ACO1, DPP4, HMOX1, and TFRC were significantly associated with breast cancer grades (all p < 0.05)." (PMID 35154262, 2021). "At the cellular level, scratching induces an increase in reactive oxygen species, Nrf2 protein, and stress response genes, including heat shock protein 70 and heme oxygenase-1, in breast cancer cells." (PMID 34657625, 2021). "Jang and coworkers suggest that 15d-PGJ2 inhibits MMP9 expression and invasion of breast cancer cells by means of a heme oxygenase-1-dependent mechanism." (PMID 34199169, 2021). "A specific inhibitor of heat-shock protein 32 (HSP32) and heme oxygenase-1 (HO-1), zinc protoporphyrin IX (ZnPPIX) has also demonstrated potential against breast cancer growth." (PMID 34207035, 2021). "In a previously used mouse breast cancer model, TAM-releasing heme oxygenase-1 (HO-1), an iron-releasing enzyme, enhanced breast cancer growth." (PMID 32726950, 2020).